YBX1 (Y-box binding protein 1)
Diseases named in the same sentence as YBX1 in open-access papers (continued):
Sharing a sentence is not in itself a finding about the gene and the disease.
tumor (continued). "To identify the common downstream targets that are up-regulated by DARS1-AS1/YBX1 and may play a tumor-promoting role in GBM, we further performed RNA-seq experiments in the absence/presence of siRNA-mediated YBX1 knockdown." (PMID 37540752, 2023). "Additionally, the Y-box binding protein 1 (YBX1), which has recently been described as a pro-metastatic gene, also correlated with the tumor content in our dataset." (PMID 36527824, 2023). "Given the nature of YBX1, reducing the m5C modification may have the potential to inhibit tumor progression by blocking YBX1 binding." (PMID 37500615, 2023). "Similarly, overexpressed YBX1 was found to be a master oncogenic contributor correlating highly with tumor progression and prognostic outcomes." (PMID 37305578, 2023). "Moreover, YBX1 mRNA expression was significantly overexpressed in tumor tissues (p < 0.05) in the TCGA database, and eQTL analysis demonstrated that the two SNPs were associated with YBX1 (p = 0.003 for rs10890208 and p = 0.024 for rs3862218)." (PMID 35861369, 2023). "Interestingly, we found a dramatic dose–response effect of YBX1 mRNA expression on the tumor stage (pnonlinear <0.05)." (PMID 35861369, 2023). "Furthermore, in these tumor types, YBX1 subnetworks are enriched for DNA repair genes (p = 5.8e-07 and p = 4.3e-05; LGG and GBM respectively) and connected to multiple E2F targets." (PMID 37200395, 2023). "Previous studies indicated that YBX-1, a transcription factor, could exert pro-oncogenic roles, promoting tumor metastasis, and engaging in the angiogenic switch." (PMID 35521747, 2022). "In summary, the data in this study show that GSDME, by virtue of its upregulation in PDAC tumour cells, mediates the transcription factor YBX1 to enter the nucleus where it promotes mucin expression, which in turn enables tumour cells to escape pancreatic enzymatic digestion." (PMID 35292781, 2022). "YBX1 (Y-box binding protein-1) is an important transcription factor for tumor progression." (PMID 34991621, 2022). "All the statistically significant parameters (p < 0.05) were then selected to draw ROC curves, which showed that the m5C-score had the highest AUC at 1-, 3- and 5-year OS compared with either the m5C-score individual genes, the m5C-methylation reader YBX1 or common PDAC serum tumor markers." (PMID 36060802, 2022). "However, mice injected subcutaneously with YBX1-KO A549 cells exhibited a much slower tumor growth rate." (PMID 35410432, 2022). "The expression of ALKBH1 (p = 0.036), ALYREF (p < 0.001), NOP2 (p < 0.001), NSUN2 (p < 0.001), NSUN4 (p < 0.001), NSUN5 (p < 0.001), NSUN6 (p < 0.001), NSUN7 (p = 0.006), and YBX1(p < 0.001) were significantly upregulated in tumor tissues compared with the adjacent mucosa." (PMID 35281843, 2022). "Additionally, we continued to observe the co-transfection changes in the tumor-promoting effect of diminished EPB41L4A-AS2 with either YBX1-siRNA or control-siRNA in SUNE1 cells." (PMID 34131399, 2021). "Suppression of YBX1 reduced tumor cell migration into the wound." (PMID 34440660, 2021). "Y-box binding protein-1 (YB-1) is one of the multifunctional proteins that have a role as a regulator in translation and transcription, and by regulating cell cycle progression at G1 / S plays an essential role in the growth and proliferation of tumor cells." (PMID 34604242, 2021). "Additionally, YBX1 participates in paclitaxel resistance in TNBC cells, but the downstream targets of YBX1 in governing tumor invasiveness and drug resistance are unclear." (PMID 34440660, 2021). "Existing studies have demonstrated that YBX1 may contribute to the progression of multiple cancers, especially in the context of promoting tumor metastasis." (PMID 34218256, 2021). "In addition, tRFs and their analogs can affect the tumor gene mRNA binding protein Y‐box binding protein 1 (YBX1), by blocking its interaction with oncogenic mRNA and destabilizing oncogene mRNAs, thereby inhibiting tumor cell infiltration." (PMID 33332661, 2021).
tumor (continued). "YBX1, a key transcription factor, is located on chromosome 1 (1p34), and as a multi-functional RNA-binding protein, it is highly overexpressed in a variety of tumors; it is established to play a role in several cellular processes, including tumor metastasis." (PMID 34218256, 2021). "These in vivo data confirmed that YBX1 promoted tumor growth by promoting MUC1 expression." (PMID 34976785, 2021). "Interestingly, several studies suggest that YBX1 is an important RNA-binding protein that can be secreted into the extracellular matrix, including tumor cell exosomes." (PMID 34218256, 2021). "In order to investigate whether FOXD3-AS1 promoted tumor progression by targeting YBX1, we conducted a series of assays." (PMID 34395290, 2021). "Gain-of-function and loss-of-function studies further validated that YBX1 regulated glycolysis- and EMT-related gene expressions and was crucial for tumor invasiveness, thus indicating that YBX1 exhibits clinical diagnostic value and is a potential metabolic target for TNBC." (PMID 34440660, 2021). "Collectively, the YBX1-mediated tumor metastasis regulation network may be a universal target for the treatment of various tumors." (PMID 34131399, 2021). "Additionally, we investigated the association of YBX1, G3BP1 and SPP1 expression with several clinical parameters including gender, age, tumor size, TNM stage and Fuhrman grade." (PMID 31481087, 2019). "Also, the percentage of tumours that present YBX1 upregulated is consistent with the data found for its protein in HBC." (PMID 31461477, 2019). "YBX1 knockdown significantly reduces tumor growth, migration, and invasion of MPM cells." (PMID 30622932, 2018). "YBX1 regulates tumor growth via CDC25a pathway in human lung cancer." (PMID 30250023, 2018). "YBX1 plays a major role in the host’s defense mechanisms against environmental cytotoxic stimuli as well as in the growth, survival, and drug resistance of tumor cells." (PMID 30647855, 2018). "Moreover, in vivo study further confirms that genetic silencing of YBX1 markedly attenuates tumor growth and this tumor-suppressive effect is largely dependent on reduced glycolysis." (PMID 29029484, 2017). "Inhibition of glycolysis completely compromises the tumor-promoting effect of YBX1 on tumor growth." (PMID 29029484, 2017). "Also using our expression data, we identified several RNA processing factors that were differentially expressed between tumor subtypes and/or regulated by estrogen receptor, including YBX1, YBX2, MAGOH, MAGOHB, and PCBP2." (PMID 28263985, 2017). "So we hypothesized that if YBX1 could bind to CDC25a promoter and up-regulate CDC25a expression to promote tumor cell overcoming cell cycle checkpoint restriction to satisfy unlimited malignant amplification." (PMID 27384875, 2016). "Y-box binding protein 1 (YBX1) is involved in the multi-tumor occurrence and development." (PMID 27384875, 2016). "Moreover, inhibition of YBX1 by siRNA suppressed tumorigenesis in a xenograft mouse model and down-regulated the expression of YBX1, CDC25a, Ki67 and cleaved caspase 3 in the tumor tissues of mice." (PMID 27384875, 2016). "Y-box binding protein 1 (YB-1) is a multifunctional protein involved in transcription and translation; high YB-1 expression promotes cell proliferation and inhibits apoptosis, tumor invasion and metastasis, and angiogenesis." (PMID 27391337, 2016). "Furthermore, we also showed that inhibition of YBX1 suppressed the expression of CDC25a in tumor tissues by IHC analysis as well as Ki 67 and stimulated cleaved caspase 3 expression." (PMID 27384875, 2016).
tumor (continued). "A recent study demonstrated a role for YBX1 in stress granule formation and tumor progression." (PMID 26549748, 2015). "We hypothesized that elevated YBX1 expression may contribute to tumour angiogenesis, by increasing endothelial cell migration." (PMID 25980435, 2015). "Overexpression of the Y-box binding protein-1 (YB-1) oncogene in human mammary epithelial cells (HMECs) drove TNBC tumor formation characterized by a multi-drug resistance phenotype, yet these cells were sensitive to LJI308 in addition to the classic RSK inhibitors BI-D1870 and luteolin." (PMID 26011941, 2015). "Given that a blood supply is critical for tumour growth, as well as dissemination, we hypothesized that elevated expression of YBX1 in MDCK cells may promote tumour angiogenesis." (PMID 25980435, 2015). "Therefore, elucidating the biological function of YBX1 in tumour progression could provide a promising foundation for therapeutic strategies." (PMID 40088428, 2025). "Similarly, tumor cells may promote oncogenic expression through m5C, as suggested by the upregulation of its readers, YBX1, YBX2, and ALYREF, which enhance mRNA transport, stability, and translation." (PMID 40918643, 2025). "Furthermore, tumor heterogeneity and compensatory signaling pathway activation may attenuate the efficacy of YBX1-targeted therapies, indicating that single-target approaches may be insufficient to fully block its oncogenic functions." (PMID 41346602, 2025). "However, overexpression of YBX1 significantly promoted the proliferation of tumour xenografts." (PMID 40088428, 2025). "For instance, YBX1 inhibition can reduce PD-L1 expression, remodel the immunosuppressive tumor microenvironment, and enhance the efficacy of immune checkpoint inhibitors (ICIs), while also reversing chemoresistance and increasing tumor sensitivity to anticancer drugs." (PMID 41346602, 2025). "Additionally, YBX1 can affect the tumour development by binding to circRNAs." (PMID 38378679, 2024). "Additionally, exploring the interaction between m5C modification and RNA-binding proteins such as YBX1 may further clarify their combined influence on mRNA stability and tumor progression." (PMID 39595099, 2024). "In addition, there is strong evidence supporting that the nuclear localization and/or overexpression of YBX1 could predict poor prognosis in patients with more than 20 different tumor types." (PMID 38254206, 2024). "Additionally, YBX1 is involved in promoting tumor progression and drug resistance." (PMID 38899362, 2024). "Furthermore, it has been established that YBX1 plays a role in the regulation of tumor immunity." (PMID 38520004, 2024). "Collectively, these results suggested that high level of YBX1 may confer “cold” tumor immune phenotype, characterized by reduced abundance of infiltrating leukocytes, diminished immune cell activation and emergence of immunosuppressive signaling, which might represent a promising therapeutic target." (PMID 36717896, 2023). "By recognizing m5C, YBX1 could stabilize mRNA to promote tumor progression." (PMID 37500615, 2023). "First, the “writer” genes NSUN1-NSUN7, the “eraser” genes TET2 and ALKBH1, and the “reader” genes ALYREF and YBX1 were significantly upregulated or downregulated in tumor tissues, suggesting these genes may be critical in m5C-related occurrence and progression of COAD." (PMID 35281843, 2022). "Notably, YBX1−/− PDAC cells barely grew a visible tumour in the pancreas of mice." (PMID 35292781, 2022). "Finally, collagen and associated signaling molecules, including ITGB1, YBX1, SPP1 and NF-κB in tumor tissues, could serve as potential biomarkers to monitor tumor progression and predict chemoresistance." (PMID 34758833, 2021). "Thus, our data suggested that YBX1 plays a tumor promotive role in NPC." (PMID 33976741, 2021). "All suggested that YBX1 may be a target gene of FOXD3-AS1 affecting tumor development." (PMID 34395290, 2021).
tumor (continued). "Finally, YBX1 knockout was shown to be sufficient to block TNBC tumor growth." (PMID 33003386, 2020). "These important results suggest that YBX1 expression and localization is controlled by a complex and as yet underappreciated regulatory network, and may strongly depend on the microenvironment of tumor cells." (PMID 26779809, 2016). "We therefore asked whether the tumor microenvironment could modulate YBX1 expression." (PMID 26779809, 2016). "Our current study emphasizes that phosphorylation of S165 on YBX1 is critical for the regulation of a subgroup of NF-κB target genes; therefore, modulation of this activity by blocking S165 phosphorylation of YBX1 could be a promising approach for inhibiting tumor growth." (PMID 26318844, 2015). "To validate these findings, we examined 27 paired clinical ccRCC samples, confirming significantly higher YBX1 and LDHA protein expression in tumor tissues versus adjacent normal tissues by western blot, with positive correlation between the two proteins." (PMID 41507134, 2026). "Concurrently, genes promoting tumor growth, including HES4, YBX1, and ARTN, were also upregulated in hmmyCAFs." (PMID 41057994, 2025). "Mechanistically, CDKL1 interacts with the transcription factor YBX1, reducing YBX1 binding to the PD-L1 promoter, thereby inhibiting PD-L1 expression, activating CD8+ T cells, and preventing tumor immune escape." (PMID 41346602, 2025). "On the basis of these results, we established that TMBIM1 modulates tumor CCL2 and PD-L1 expression through the regulation of YBX1." (PMID 40083936, 2025). "YBX1 plays an important role in HCC, including tumour progression, sorafenib resistance, anti‐tumour immune response and so forth." (PMID 40088428, 2025). "For instance, circNEIL3 exerts its metastasis inhibitory effect through direct interaction with the oncoprotein Y-box binding protein 1 (YBX1), thereby promoting Nedd4L-mediated YBX1 proteasomal degradation to retard tumor metastasis." (PMID 40034598, 2025). "The proto-oncogene heparin-binding growth factor (HDGF) mRNA is methylated by NSUN2, and YBX1 stabilizes HDGF mRNA by binding to m5C methylation sites and recruiting ELAVL1, thereby promoting tumor development." (PMID 40370440, 2025). "Prior research has established that in BCa, H3K18la promotes tumor proliferation and migration by up-regulating LCN2 expression, and facilitates cisplatin resistance by enhancing the expression of YBX1 and YY1." (PMID 41199784, 2025). "Their interaction and positive feed-forward loop, perpetuated by JMJD6 and YBX1 inter-regulation, culminates in HOTAIR induction, which in turn is known to drive tumour progression." (PMID 40855961, 2025). "CircASH2 drives phase separation of YBX1 to increase TPM4 transcripts degradation and suppresses HCC metastasis by altering the tumor cytoskeleton structure." (PMID 38969650, 2024). "Liquid–liquid phase separation of YBX1 is increased by circASH2, which leads to increased TPM4 transcript decay, thereby regulating metastasis by altering the tumour cytoskeletal structure." (PMID 39625183, 2024). "In these tumor types, high expression of ALYREF and YBX1 is observed in advanced pathologic TNM stages as well as clinical grade." (PMID 38238581, 2024). "Meanwhile, TUG1 interacted with YBX1 to facilitate the upregulation of PD‐L1 and CD47 transcriptionally, which ultimately regulated tumor immune evasion." (PMID 38981064, 2024). "As well, xenograft tumours derived from KMT2D‐ and YBX1‐knockdown cells expressed significantly lower levels of c‐Myc and SENP1." (PMID 38967349, 2024). "In our study, hsa-miR-1287-5p downregulated YBX1 by directly binding to its 3’ UTR, while circRAD23B indirectly upregulated YBX1 through the adsorption of hsa-miR-1287-5p, resulting in accelerated tumour proliferation and increased carboplatin resistance." (PMID 38273320, 2024).
tumor (continued). "To understand the interactions between the expression of m5C readers and the tumor microenvironment, we analyzed the correlations between expression of ALYREF and YBX1 and various immune cell populations." (PMID 38238581, 2024). "Peroxiredoxin-4, bromodomain-containing protein 2 and Y-box-binding protein 1 potentiated HCC development and tumor invasion via Wnt/β-catenin pathway 29-31." (PMID 37649614, 2023). "MYC bound to the promoter containing the consensus MYC binding motif (CACGTG) of YBX1, CD133 and muscle satellite/RMS tumor propagating cell markers MYF5 and PAX7." (PMID 37345125, 2023). "For example, in GC patients, YBX1 binds with FOXC2 (Forkhead box protein C2) mRNA, which is m5C-modulated by NSUN2, to enhance its tumor-promoting ability." (PMID 37325635, 2023). "Here the authors show that PI3K-phospho-YBX1 axis promotes tumour growth in basal subtype of HNC, while unphosphorylated YBX1 acts as a suppressor of metastasis in the mesenchymal subtype with inactive PI3K signalling." (PMID 36949044, 2023). "After m5C modulation and binding to m5C readers, such as YBX1, the transcriptional activity of PIK3R1, PCYT1A and FOXC2 mRNA was increased, while tumor-suppressive p57Kip2 mRNA was destabilized as a result of m5C modulation in the 3’-UTR." (PMID 37325635, 2023). "In contrast, the expressions of NSUN3, NSUN4, NSUN7, TRDMT1, DNMT1, YBX1, and TET2 were low in tumors and had a tumor-suppressive effect." (PMID 36661693, 2022). "The ensuing question was how CRC tumor cells led to high expression of the m5C-modified regulators NSUN5 and YBX1 in immune cells of peripheral blood." (PMID 36211353, 2022). "Another study reported that circFOKX2 contributed to tumor progression in PDAC by sponging miR-942 and interacting with YBX1 and hnRNPK." (PMID 36008392, 2022). "In vitro co-culture experiments also demonstrated that CRC tumor cells promoted NSUN5 and YBX1 expression in immune cells, resulting in elevated m5C levels." (PMID 36211353, 2022). "It is worth noting that the expression of YBX1 and SOX2 in tissues adjacent to tumor area is significantly higher than that in normal tissues." (PMID 36397101, 2022). "Consistently, YBX1, MUC1 and MUC13 were upregulated in tumour tissues of patients compared to the paracancerous tissues." (PMID 35292781, 2022). "The activation of the NSUN2/YBX1/HDGF axis was proven to promote cell growth, tumor progression and metastasis." (PMID 34512153, 2021). "Our study firstly identified that lncRNA GAS6-AS1 and its related GAS6-AS1/YBX1/MYC axis contribute to poor prognosis of AML patients, and exert oncogenic roles in regulating cellular proliferation and tumor progression." (PMID 34753494, 2021). "The results showed that while YBX1 silencing reduced tumor growth, MUC1 overexpression significantly promoted tumor growth." (PMID 34976785, 2021). "Two animal models demonstrated that YBX1 and MUC1 were key genes for tumor growth, and blood metastasis in vivo." (PMID 34976785, 2021). "Here, after YBX1 knockout by CRISPR/Cas9, we tested the absolute effect of YB-1 on cell proliferation, clonogenic activity, and tumor growth." (PMID 33003386, 2020). "The R205 methylation of YBX1 is important for its interaction with p65, revealing a novel cooperativity between YBX1 and PRMT5 that dynamically modulates NF-κB activity and target gene expression to render a tumor-promoting effect in CRC cells." (PMID 32985589, 2020). "To further verify the effect of YBX1 on sensitivity to cisplatin of NSCLC cells, we used cisplatin on nude mice on the seventh day after injection of tumor cells." (PMID 32561752, 2020). "On the other hand, circFAT1(e2) is able to bind directly to Y-box binding protein-1 (YBX1) and block tumor-promoting abilities of GC cells." (PMID 32708088, 2020). "Thus, targeting YBX1 stabilization may be an alternative approach to prevent tumor relapse." (PMID 32178290, 2020).